PBK (PDZ binding kinase)
Diseases named in the same sentence as PBK in open-access papers (continued):
Sharing a sentence is not in itself a finding about the gene and the disease.
glioma (23 papers, 2015 to 2024). A benign or malignant brain and spinal cord tumor that arises from glial cells (astrocytes, oligodendrocytes, ependymal cells). "Western blot results showed a significant reduction in EIF4E expression after PBK knockdown in glioma cell line HS683." (PMID 39649886, 2024). "Western blot analysis was also performed to detect EIF4E protein expression, one of the key hub genes, after PBK knockdown in the HS683 glioma cell line." (PMID 39649886, 2024). "Studies support the functional role of PBK in conferring tumor aggressiveness in GBM, showing that the treatment of glioma cells with PBK inhibitors reduces tumor volume in vivo." (PMID 36300592, 2023). "After calculating the hazard ratio and confidence interval, we observed that 8 hub genes in hub network 1 were related to the poor prognosis of gliomas, including PBK, KIF2C, CENPE, KIF14, MND1, FAM83D, NEIL3, and CDKN3." (PMID 35387222, 2022). "Previous studies have reported that high PBK expression is associated with a poor prognosis in patients with several types of malignancies, such as kidney renal clear cell carcinoma (KIRC), lower grade glioma (LGG), and liver hepatocellular carcinoma (LIHC)." (PMID 35203508, 2022). "It has been reported that CDK4 knockdown impedes the colony formation and cell proliferation of glioma, and that PBK and SLC2A3 could be a potential prognostic factor and therapeutic target for GBM treatment." (PMID 36358948, 2022). "Having established a significant role for PBK in three gliomas we set out to test whether inhibition of PBK would affect a large number of tumors and to gauge how well normal cells fare under a treatment scenario." (PMID 26081429, 2015). "CENPF, TOP2A, UBE2C, PBK, and MKI67 were strongly expressed in glioma clusters, indicating the presence of progenitor cells." (PMID 39333557, 2024). "More importantly, PBK expression is much higher in GBM than in normal tissue and is significantly correlated with glioma grade." (PMID 39649886, 2024). "This study investigates the gene expression characteristics of glioma-initiating cells (GIC), an important subgroup of glioblastoma (GBM), after knockdown of PBK (PDZ-binding kinase)." (PMID 39649886, 2024). "Another study demonstrated that targeting PBK/TOPK with HI-TOPK-032 decreased growth and survival of glioma initiating cells in vitro and attenuated tumor growth in vivo." (PMID 35126305, 2021). "We found an overexpression of DLGAP5, NEK2, and PBK, while the expression of SF1, PTEN, ATRX, and DAXX was downregulated in tumor tissues as compared to normal tissues of the patients with glioma." (PMID 35095717, 2021). "We are currently working on gene knockdowns of several genes from the presented list and have recently shown that targeting PBK/TOPK decreases growth and survival of glioma initiating cells in vitro and attenuates tumor growth in vivo." (PMID 26295306, 2015). "From the transcriptome data analysis results in the public database, it was found that CDK4, PBK, ANGPTL2, TMEM100, and MEX3A were significantly up-regulated in the glioma samples compared with the normal samples, whereas NEGR1 and SLC2A3 were down-regulated in the glioma samples at the mRNA level." (PMID 36358948, 2022).
melanoma (21 papers, 2007 to 2026). A malignant, usually aggressive tumor composed of atypical, neoplastic melanocytes. "Arsenite treatment was confirmed to cause phosphorylation of PBK/TOPK, which alleviated the apoptosis induced by arsenite treatment in melanomas." (PMID 33670114, 2021). "Finally, we investigated the therapeutic efficacy mRNA vaccine encoding neoantigens of PDZ-binding kinase (PBK) and actinin alpha 4 (ACTN4), which were identified from the B16F10 murine melanoma mutanomes." (PMID 36311701, 2022). "Thus, the combined inhibition of PBK/TOPK with arsenite treatment is a potential therapy for melanomas." (PMID 33670114, 2021). "This list included several oncogenes, namely MIR544A, MIR146B, FAM83A (also known as tumor antigen BJ‐TSA‐9), the cancer‐germline genes PBK (PDZ binding kinase) and PRAME (preferentially expressed antigen in melanoma), and GCKR that, with PRAME, is a downstream target of the BCR‐ABL protein." (PMID 29575763, 2018). "Notably, the expression of the PBK protein in melanoma has not been reported; however, moderate nuclear and cytoplasmic positivity was observed in the melanoma IHC images we obtained from the HPA database but requires further confirmation in the future." (PMID 34603451, 2021).
leukemia (20 papers, 2006 to 2026). A malignant (clonal) hematologic disorder, involving hematopoietic stem cells and characterized by the presence of primitive or atypical myeloid or lymphoid cells in the bone marrow and the blood. "Based on the complex classification of leukemia, the expression and role of PBK in each type of leukemia must be further studied." (PMID 34603451, 2021). "TPA-induced differentiation and growth arrest of HL-60 leukemia cells led to profound down-regulation of PBK/TOPK." (PMID 23675007, 2006). "Increased PBK/TOPK expression has been observed in highly proliferative malignant cell lines, and PBK/TOPK expression is down-regulated during terminal differentiation of leukemia cells." (PMID 23675007, 2006). "It has been observed that LPS increases PBK levels in leukemia cells while up-regulating the expression of inducible nitric oxide synthase (iNOS), suggesting that PBK may be involved in the inflammatory response or in inflammation-related diseases." (PMID 37817228, 2023). "Meanwhile, lower expression of the PBK/TOPK mRNA was observed in the leukemia datasets." (PMID 34603451, 2021). "As a mitotic kinase, PBK/TOPK is important for the proliferation, progression, and metastasis of many cancers, including leukemia and myeloma, among others." (PMID 33670114, 2021). "Third, expression of PBK/TOPK was found to be up-regulated in a variety of neoplastic cell lines and in some clinical samples from patients with leukemia, myeloma." (PMID 23675007, 2006). "In this paper, additional evidence is presented to support the role of PBK/TOPK in the differentiation of leukemia HL-60 cells; it indicates that gossypol can induce differentiation in leukemia cells." (PMID 23675007, 2006). "This study is the first to identify gossypol’s pro-differentiated effects on the leukemia cell line, and it induced differentiation through the PBK (PDZ-binding kinase)/TOPK (T-LAKcell-originated protein kinase) (PBK/TOPK) pathway." (PMID 23675007, 2006). "Even though RAF is not significantly differentially expressed in the leukaemia signature itself, it is the first neighbour of significantly differentially expressed genes of the disease, such as PBK, OIP5 and CDC25A, and may thereby exert indirect effects on the system." (PMID 34131166, 2021).
lung adenocarcinoma (18 papers, 2015 to 2026). A carcinoma that arises from the lung and is characterized by the presence of malignant glandular epithelial cells. "In this study, we aimed to investigate the role of PBK in lung adenocarcinoma (LUAD) progression, prognosis, and immune evasion." (PMID 37993518, 2023). "Moreover, miR-216b-3p was found to inhibit lung adenocarcinoma cell growth by directly binding PBK/TOPK and negatively regulating its expression." (PMID 33670114, 2021). "PBK/TOPK overexpression could also predict poor prognosis, including shortened overall survival and time to recurrence, because of its effect on promoting tumor metastasis in patients with stage I lung adenocarcinoma and non-small-cell lung cancers (NSCLC)." (PMID 33670114, 2021). "Besides, PBK also played important roles in other cancers, including lung adenocarcinoma." (PMID 31781484, 2019).
gastric cancer (17 papers, 2016 to 2026). A primary or metastatic malignant neoplasm involving the stomach. "We next performed an immunohistochemistry analysis of 385 gastric cancer patients to evaluate the relationship between expression of PSMB8 or PBK and clinicopathological characteristics." (PMID 26894977, 2016). "Consistent with our microarray results, a Kaplan-Meier survival analysis revealed that gastric cancer patients displaying high protein expression of either PSMB8 or PBK had a decreased survival rate." (PMID 26894977, 2016). "Although it has been reported that carcinoma cell motility and invasiveness occur via the PI3K and MAP kinase pathways, we observed unaltered activation of Akt, ERK, or p38 following PSMB8 or PBK downregulation in gastric cancer." (PMID 26894977, 2016). "We propose that PSMB8 and PBK could be useful biomarkers for identifying gastric cancer patients with a poor prognosis." (PMID 26894977, 2016). "Knockdown of PSMB8 and PBK decreased gastric cancer cell migration and invasion, respectively." (PMID 26894977, 2016). "PSMB8 and PBK were predictive of gastric cancer prognosis and could be potential gastric cancer subtype-specific biomarkers." (PMID 26894977, 2016). "However, knockdown of each gene significantly decreased gastric cancer cell migration and invasion, suggesting that PSMB8 and PBK are involved in gastric cancer progression." (PMID 26894977, 2016). "Also, in gastric cancer cell line studies, migration and invasion were reduced by knockdown of PBK." (PMID 28978135, 2017). "PBK/TOPK is often overexpressed in gastric cancer; thus, it could be a crucial molecular marker to determine the malignant properties of gastric cancer cells and a target for molecular therapy in gastric cancer patients." (PMID 34066486, 2021). "Although we clearly suggested that PSMB8 and PBK promote the migration and invasion of gastric cancer cells, PSMB8 and PBK are not sufficient to proliferation by themselves in gastric cancer cells." (PMID 26894977, 2016). "Furthermore, immunohistochemistry analysis of 385 gastric cancer patients revealed that increased nuclear expression of PSMB8 and PBK was correlated with depth of invasion, lymph node metastasis, and lower survival rates." (PMID 26894977, 2016). "We next performed immunohistochemistry staining to detect PSMB8 and PBK protein expression in 385 gastric cancer specimens that were not the same as those used in the microarray studies." (PMID 26894977, 2016). "The molecular mechanism by which PSMB8 and PBK promote gastric cancer cell progression has not been elucidated." (PMID 26894977, 2016). "We focused on PSMB8 and PBK, whose functions in gastric cancer have not been reported." (PMID 26894977, 2016). "Although PBK is also involved in many cellular functions, including tumor development, cell growth and cell death, and is highly expressed in many cancers, its role in gastric cancer has not been reported." (PMID 26894977, 2016).
hepatocellular carcinoma (16 papers, 2016 to 2025). A malignant tumor that arises from hepatocytes. "PBK is upregulated in hepatocellular carcinoma which is a risk factor of survival and associated with antitumor immunity in hepatocellular carcinoma." (PMID 37120564, 2023). "Bioinformatics analysis revealed that NDC80 and PBK can serve as biomarkers for HBV-associated hepatocellular carcinoma." (PMID 34917088, 2021). "A previous study has established a prognostic risk model for hepatocellular carcinoma (HCC) based on five ARGs (BAK1, SPP1, BSG, PBK, and DAP3)." (PMID 40901678, 2025). "PBK is aberrantly overexpressed in many cancers, such as adrenocortical carcinoma, hepatocellular carcinoma, and pancreatic cancer." (PMID 38215156, 2024). "High expression of PBK is significantly correlated with poor survival and immune infiltrates in hepatocellular carcinoma." (PMID 35065633, 2022). "PBK overexpression promotes the metastasis of hepatocellular carcinoma by activating the ETV4-uPAR signaling pathway." (PMID 33952716, 2021). "PBK/TOPK protein has been identified as a useful indicator for histopathological differentiation between cholangiocarcinoma and hepatocellular carcinoma, and low expression of PBK/TOPK is predictive of poor survival in cholangiocarcinoma patients." (PMID 33670114, 2021). "Suppression of PBK/TOPK not only impaired the proliferation of hepatocellular carcinoma cells but also resulted in an inhibitory effect of fibroblast growth factor (FGF21) treatment on D-galactose (D-gal)-induced hepatocyte apoptosis." (PMID 33670114, 2021). "PDZ-binding kinase (PBK) has been implicated in the malignant process of cancers, but its role and clinical significance in hepatocellular carcinoma (HCC) remains unclear." (PMID 28525379, 2017). "The ceRNA regulatory network involving CBX2, PBK, and AP002478.1 influences the progression of hepatocellular carcinoma." (PMID 38355480, 2024). "Multiple database analysis shows that PBK was highly expressed in many types of tumors, including hepatocellular carcinoma, and was significantly related to tumor stage (P=0.0089), age (P=0.0131), and race (P=0.0024) of HCC patients." (PMID 35065633, 2022). "Additionally, PBK promotes metastasis and resistance to oxaliplatin by regulating pathways such as ETV4-uPAR and PTEN in hepatocellular carcinoma." (PMID 37120564, 2023). "However, the role of PBK in hepatocellular carcinoma (HCC) remains unclear." (PMID 35065633, 2022).
lymphoma (14 papers, 2013 to 2026). A malignant (clonal) proliferation of B- lymphocytes or T- lymphocytes which involves the lymph nodes, bone marrow and/or extranodal sites. "Median expression levels were invariably higher for AURKB, BCAT1, BIRC5, BUB1B, PBK and RACGAP1 and lower for FOSB, MAP3K1 and RIN3 by qPCR in lymphoma versus normal B cell samples in both species." (PMID 24130802, 2013). "Similarly, in high-grade lymphomas, PBK/TOPK overexpression forms part of a c-Myc-E2F1-PBK axis, and targeting this pathway reduces lymphoma cell growth and survival." (PMID 41362722, 2026).
glioblastoma (13 papers, 2019 to 2026). The most malignant astrocytic tumor (WHO grade IV). "In glioblastoma, PBK inhibition improves radiotherapy efficacy by regulating CCNB2, a key factor in tumorigenesis and radio-resistance." (PMID 41362722, 2026). "Furthermore, the two m6A sites of PDZ binding kinase (PBK) are regulated by SRSF7 in glioblastoma cells through recognition by IGF2BP2." (PMID 35625706, 2022). "Moreover, upregulation of PBK/TOPK in the peritumoral brain zone of glioblastoma multiforme (GBM) contributed to its vulnerability to tumor recurrence." (PMID 33670114, 2021). "Investigated the role of PDZ-binding kinase (PBK) in glioblastoma multiforme (GBM) and its potential as a therapeutic target." (PMID 39649886, 2024). "The molecular docking results confirmed the potential of Dapagliflozin in inducing apoptosis by arresting the cell cycle by targeting CDK1, PBK, and CHEK1 in glioblastoma." (PMID 38003585, 2023). "This study discusses our assessment of CDK1/PBK/CHEK1′s potential as theragnostic and prognostic markers in glioblastoma." (PMID 38003585, 2023). "However, the simultaneous inhibition of the chemo radio-resistant CDK1/PBK/CHEK1 oncogenic signature in glioblastoma has never been explored despite the existing cell cycle crosstalk amongst these genes." (PMID 38003585, 2023).
cervical cancer (12 papers, 2016 to 2024). A primary or metastatic malignant neoplasm involving the cervix. "PBK has been demonstrated to be linked to aggressive phenotype in prostate-, breast- and cervical cancer." (PMID 28978135, 2017). "The upregulation of endogenous PBK/TOPK augmented resistance of human HeLa cervical cancer cells to TRAIL-induced apoptosis, while PBK/TOPK knockdown noticeably increased doxorubicin-mediated apoptosis." (PMID 33670114, 2021). "We have suggested that PBK plays a key role in TRAIL or doxorubicin resistance of human HeLa cervical cancer cells." (PMID 32237067, 2020). "We previously reported that PBK confers TRAIL or doxorubicin resistance to HeLa cervical cancer cells by regulating IκBα phosphorylation." (PMID 32237067, 2020). "Mechanically, to explore whether solamargine regulates the Erk pathway by targeting a specific mRNA, we selected genes reported in recent years to regulate the Erk pathway in cervical cancer, including PBK, RACK1, CXCL3, TRIP4, and SEMA3C, for study." (PMID 36345403, 2022). "In order to investigate whether solamargine regulates the Erk signaling pathway by modulating target mRNAs, we screened out genes that regulate this pathway in cervical cancer including PBK, RACK1, CXCL3, TRIP4, and SEMA3C, which have been reported in the literature in recent years." (PMID 36345403, 2022). "Then, the top 40 hub genes were conducted to evaluate the expression and prognostic values of cervical cancer and 7 upregulated (BUB1, CCNB1, CDK1, AURKB, KIF11, PBK, NUSAP1) and 1 downregulated (ESR1) hub genes were selected to have significant values as biomarkers." (PMID 33682613, 2021). "After combination of the expression pattern and survival analysis, eight upregulated hub gens (CCNB1, BUB1, CDK1, AURKB, KIF11, PBK and NUSAP1) stood out with dramatical upregulation in cervical cancer and were significantly correlated with good prognosis of cervical cancer (P < 0.05)." (PMID 33682613, 2021).
nasopharyngeal carcinoma (11 papers, 2016 to 2025). A carcinoma arising from the nasopharyngeal epithelium. "Here we demonstrate that a pro-oncogenic kinase PBK, the expression of which is associated with immune infiltration in nasopharyngeal carcinoma (NPC), stimulates the expression of CD276 epigenetically." (PMID 33431797, 2021). "PDZ-binding kinase (PBK), whose expression is associated with immune infiltration in nasopharyngeal carcinoma (NPC), also plays an important role in CD276 expression regulation." (PMID 33842369, 2021). "In nasopharyngeal carcinoma, PBK-mediated phosphorylation of MSL1 enhances CD276 transcription and facilitate immune evasion, implicating the MSL complex in tumor-associated immune regulation." (PMID 41409271, 2025). "In nasopharyngeal carcinoma, PBK-mediated phosphorylation of MSL1 enhances MSL complex occupancy at the CD276 promoter, driving transcriptional activation of CD276 and promoting immune evasion." (PMID 41409271, 2025).
cholangiocarcinoma (8 papers, 2015 to 2022). A carcinoma that arises from the intrahepatic biliary tree (intrahepatic cholangiocarcinoma) or from the junction, or adjacent to the junction, of the right and left hepatic ducts (hilar cholangiocarcinoma). "A recent study showed that PBK/TOPK down-regulation is significantly associated with poor prognosis in patients with cholangiocarcinoma." (PMID 30286126, 2018). "The result has shown that PBK expression was extremely higher in most common tumor tissues, such as colon adenocarcinoma, cholangiocarcinoma, breast invasive carcinoma, liver hepatocellular carcinoma, and so on." (PMID 35065633, 2022).
esophageal cancer (7 papers, 2019 to 2025). A primary or metastatic malignant neoplasm involving the esophagus. "PBK upregulation is linked to the development of ovarian plasma membrane and unfavorable prognosis in patients with ovarian plasma cystic adenocarcinoma, esophageal cancer, and gastric adenocarcinoma." (PMID 39297018, 2024).